INS (insulin)
Diseases named in the same sentence as INS in open-access papers (continued):
Sharing a sentence is not in itself a finding about the gene and the disease.
Insulin resistance (continued). "Therefore, we hypothesized that the expression levels of insulin signaling-related factors are upregulated in adipose tissues of KK/Ay mice, in which blood insulin resistance suppression and blood glucose intolerance by oral LPS administration were observed." (PMID 36902049, 2023). "First, the lack of change in glucose or insulin responses could be because 96 hours of drug removal is insufficient time to see the effects of statins causing insulin resistance." (PMID 37465091, 2023). "Moreover, insulin initiates intracellular signaling cascades upon binding to its receptor on muscle cells, triggering events that regulate glucose metabolism, which is altered in cases of insulin resistance." (PMID 38137918, 2023). "Over time, as beta-cells deplete, insulin resistance may remain high, but insulin levels lower." (PMID 37367904, 2023). "In 2017, Aguayo Mazzucato’s experiments demonstrated that insulin resistance in insulin-resistant mouse models could increase the expression level of senescent markers of pancreatic β-cells, such as p16INK4a, IGF-1R, and BAMBI, thereby accelerating the senescence of pancreatic β-cells." (PMID 37868908, 2023). "Therefore, we reasoned that ablating NOX4 and abrogating the resultant H2O2-dependent NFE2L2 antioxidant defense response, and, in particular, reducing SOD2, would promote mitochondrial oxidative stress to diminish insulin signaling and promote insulin resistance." (PMID 38060313, 2023). "Besides the elevated free fatty acid levels, other substances secreted by the adipocytes that are augmented (tumor necrosis factor—TNF-α, resistin) or decreased (adiponectin) in obesity inhibit insulin secretion and insulin-mediated glucose uptake, and lead to insulin resistance." (PMID 37367903, 2023). "Therefore, the significantly increased risk of T2D associated with FPG > 4.5 mmol/L in the Chinese population and FPG > 5.2 mmol/L in the Japanese population observed in this study might have been due to defective insulin secretion and insulin resistance." (PMID 36872318, 2023). "Furthermore, Lactococcus lactis lowered the respiratory exchanges ratio, increased night cycle activity, increased serum gastric inhibitory polypeptide (GIP) which stimulates insulin production, and lowered resistin, the adipose tissue hormone that is a biomarker of insulin resistance." (PMID 37763997, 2023). "Metformin may inhibit the release of calpain 2 from exosomes, interfere with IR splitting (through the pathway of knocking out calpain 2 and γ-secretase), restore the functions of IRS-1 and Akt, and re-establish insulin signaling, thereby alleviating insulin resistance, enhance insulin sensitivity." (PMID 36818396, 2023). "A comprehensive report published by Health and Human Services, USA, in 2015 indicated that physical activity significantly improved abnormal glucose tolerance primarily caused by insulin resistance, rather than when it was due to deficient amounts of circulating insulin." (PMID 37763706, 2023). "Hence, the pathophysiological connection between ACBP and insulin resistance may lead to enhanced insulin secretion of beta cells in order to overcome this insulin resistant state." (PMID 37872629, 2023). "Dietary betaine supplementation reverses insulin resistance in an in vitro model, and in both in vitro and in vivo models, betaine normalizes downstream signaling pathways involved in gluconeogenesis, perhaps by improving phosphorylation of early steps in the insulin signaling cascade." (PMID 37238121, 2023). "The abundances of fecal isobutyric acid negatively correlated with fasting plasma glucose, insulin, cholesterol, triglycerides, tumor necrosis factor-α, plasminogen activator inhibit-1, monocyte chemotactic protein-1 and homeostatic model assessment of insulin resistance (p < 0.01)." (PMID 38004641, 2023). "Notably, PJ1-1 increased insulin sensitivity and ameliorated insulin resistance." (PMID 37233464, 2023).
Insulin resistance (continued). "Furthermore, insulin resistance may contribute to these findings as insulin is known to inhibit lipolysis." (PMID 37741873, 2023). "A dose-related increase in insulin resistance was noted in patients treated with higher doses of recombinant GH (0.045 mg/kg/day vs 0.0675 mg/kg/day and 0.09 mg/kg/day), as evidenced by increased area under the curve (AUC) for insulin during OGTT, insulinogenic index, and urinary C-peptide." (PMID 36875465, 2023). "With the same levels of glucose clearance whether or not the mice were treated with rcREG3A, there was a significant decrease in circulating insulin levels at 15 min and a trend at 30 min after a glucose tolerance test, suggesting better control of insulin resistance in those treated with rcREG3A." (PMID 36918710, 2023). "Moreover, CUMS aggravated insulin resistance in mice and inhibited the insulin pathway in iWAT." (PMID 37692113, 2023). "In mice, daidzein may ameliorate insulin resistance in obesity via direct modulation of hepatic ab initio adipogenesis and insulin signaling, and alter adipocyte metabolism to indirectly control obesity and reduce NAFLD by regulating adipokine expression through PPAR γ." (PMID 36860686, 2023). "NIDDM is characterized by insulin resistance, in which the primary insulin-target organs, such as skeletal muscle, liver, and adipocytes are poorly responsive to insulin action, which may combine with reduced insulin secretion caused by a progressive loss of β-cell function." (PMID 36837888, 2023). "As a result, increased CM synthesis by the intestine is a significant feature not only in people with type 2 diabetes but also in insulin-resistant people who are not diabetic, suggesting that insulin resistance is likely to be the primary mechanism implicated in its pathogenesis." (PMID 38303975, 2023). "Meanwhile EP, Zn(II), and their complex administration had significantly inhibited the increasing HOMA-IR index and increased QUICKI index (vs. the model group), especially for HEZ, indicating that EZ could effectively inhibit the degree of insulin resistance and enhance insulin sensitivity." (PMID 37569125, 2023). "Increased blood lipid concentrations result in insulin resistance in peripheral tissues, impaired glucose absorption and usage and lipid metabolism, blood circulation and lipid aggregation in various tissues, and metabolic signaling pathways that regulate insulin secretion in pancreatic β-cells." (PMID 37009872, 2023). "However, it is worth noting that additional findings indicate that the disruption of IRS-1 in mice hinders growth, yet it does not lead to the development of diabetes due to the compensatory increase in insulin secretion to counteract the mild insulin resistance." (PMID 37850091, 2023). "For patients with insulin resistance, exercise can reduce intestinal inflammation and modify the profile of the gut microbiome, such as the genera Clostridium and Blautia, which are closely correlated with improvements in glucose homeostasis and insulin sensitivity." (PMID 37110325, 2023). "Insulin resistance is a major feature in T2DM development and may be caused by an insulin signalling defect, inflammatory cytokines, lipotoxicity, glucose transporter defect, amyloid formation for β-cell dysfunction, OS, mitochondrial dysfunction, excess fatty acid, or lack of the cretin effect." (PMID 37497112, 2023). "It is possible that metabolomics may be more closely associated with insulin resistance than with high levels of insulin (especially in the fasting state), although we could not directly evaluate this speculation." (PMID 37367904, 2023). "Across three MAs and one SR examining the effect of SSFR on insulin sensitivity, most of the evidence suggests a possible improvement in obesity-associated insulin resistance, however, there was a lack of clarity regarding the extent of the effect and clinical significance." (PMID 36200436, 2023).
Insulin resistance (continued). "Additionally, leptin affects both peripheral insulin resistance and the insulin glucose pathways." (PMID 36838411, 2023). "In addition, increased ROS levels may interfere with insulin signaling and lead to insulin resistance." (PMID 36838862, 2023). "If lower maternal serum SHBG were to reflect insulin resistance, study findings suggest that insulin insensitivity could be occurring in the early second trimester of pregnancies associated with autism even in the absence of subsequent clinical PNMS manifestations." (PMID 37573326, 2023). "Similarly, andrographolide reportedly blocked the NF-κB signaling pathway induced by TNF-α in adipocytes, suggesting that it might reduce insulin resistance by modulating the insulin signaling pathway and improving glucose uptake." (PMID 36865924, 2023). "Prediabetes is characterized by insulin resistance and DM is characterized by hyperglycemia due to reduced insulin action and/or relative deficiency in pancreatic insulin secretion with or without decreased insulin sensitivity in target organs." (PMID 37675136, 2023). "Furthermore, a significant reduction was observed in the insulin level (μIU/mL) [MD (−1.27); 95% CI: (−2.39)–(−0.15), p = 0.003], insulin resistance (HOMA-IR) [MD (−0.61); 95% CI: (−1.02)–(−0.21), p = 0.03], and body-mass index (Kg/m2) [MD (−0.8) 95% CI: (−1.51)–(−0.08), p = 0.03]." (PMID 37893507, 2023). "In addition to causing adipose tissue inflammation and insulin resistance, these factors can also affect the insulin sensitivity of skeletal muscle and liver through blood circulation, leading to systematic insulin resistance, and further aggravating glucose metabolism disorder." (PMID 37153000, 2023). "Besides, HFD induced the glucose intolerance and insulin resistance with significantly increased levels of fasting serum insulin, blood glucose, and homeostatic model assessment for insulin resistance (HOMA-IR), and these adverse effects can be mitigated by OCA treatment and FMT." (PMID 37258543, 2023). "MET is an insulin booster that enhances insulin sensitivity, and consequently, it may be beneficial from the perspective of wound healing, as insulin resistance has been shown to impede the healing of excisional skin wounds by delaying contraction and re-epithelialization." (PMID 37250977, 2023). "In a recent study, patients with obesity but no symptoms of diabetes were investigated and it was found that DAG content and PKCε activation were the most significant predictors of hepatic insulin resistance and it could explain that 60% of the differences in hepatic insulin sensitivity." (PMID 37867509, 2023). "Moreover, elevated blood glucose and insulin resistance were improved by THC possibly via a regulation of the hepatic insulin signaling cascade, gene transcription involved in glucose metabolism, and reduction of macrophage infiltration in the liver and adipose tissue." (PMID 37876615, 2023). "Additionally, insulin secretion and insulin resistance might also be genetically determined and as such affect intrauterine growth." (PMID 37334297, 2023). "Thus, NK may not only assist with regulating glycaemic control in T2DM, reducing insulin demand and exposure, but may help to ameliorate further MCP-1-mediated insulin resistance, further reducing insulin demand." (PMID 37958602, 2023). "Therefore, compensatory hypersecretion of insulin can induce insulin resistance." (PMID 37187760, 2023). "SENDs can be effective in restoring insulin secretion by reducing β cell death and restoring β cell function thanks to its highly potent antioxidant properties, while SENDs may have limited efficacy in alleviating insulin resistance." (PMID 37408520, 2023). "In clinical settings, assessing insulin sensitivity and insulin resistance can be accomplished by performing repeated intravenous glucose tolerance tests to measure sensitivity and by evaluating the homeostatic model for insulin resistance (HOMA-IR) to measure resistance." (PMID 38001527, 2023).
Insulin resistance (continued). "Hyperinsulinemia has also been considered as a cause rather than a consequence of insulin resistance, since elevated plasma insulin levels may chronically reduce the number and the activity of the insulin receptors, leading to insulin resistance." (PMID 36564463, 2022). "Hypoxic (15% hypoxic) mothers improved glucose tolerance and insulin sensitivity compared to normoxic mothers and did not develop insulin resistance in late pregnancy, which was associated with upregulation of HIF-1α and its target genes, which in turn increased glycolysis." (PMID 36496995, 2022). "With regard to GDM exposure, high glucose levels are associated with lower HRV and higher HR in adults and in children, and high fetal glucose levels such as those found in GDM might affect the maturating ANS either directly or indirectly via high fetal insulin levels and fetal insulin resistance." (PMID 36558379, 2022). "Notably, we could also show that the use of DPP4 inhibitors was associated with a lower IGR and that metformin use was more prevalent in those with high insulin levels, indicative of insulin resistance." (PMID 36056607, 2022). "However, two weight loss dietary RCTs with more than 1-year duration showed that serum glucose and insulin levels decreased and insulin resistance improved in non-risk allele subjects with overweight/obesity." (PMID 36155628, 2022). "In addition, their use leads to an improvement in the lipid profile, a reduction in blood pressure, as well as a reduction in insulin resistance with an improvement in blood glucose and insulin levels, which is particularly important in the case of patients with PCOS syndrome." (PMID 36364814, 2022). "Additionally, this study found that cows which experienced delayed ovulation in their first lactation had demonstrated insulin resistance at 6 months of age, as their glucose levels remained significantly higher after feeding despite a rise in insulin occurring at this time." (PMID 36230395, 2022). "Conversely, another study showed that acetate enhances glucose-stimulated insulin secretion through the activation of the parasympathetic nervous system, although these effects appear to be related to hyperphagia, ectopic lipid deposition, and insulin resistance." (PMID 35634505, 2022). "Also, in patients without a DM history, insulin resistance and lower insulin/C-peptide sensitivity were statistic associated with T staging." (PMID 35299970, 2022). "However, adiposity contributes to insulin resistance increasing plasma insulin and by extension might affect HM insulin." (PMID 36407523, 2022). "It has been reported that TNF-α is the key mediator of insulin resistance because it can reduce insulin signaling by potently inhibiting insulin receptor (IR) tyrosine kinase, which might reduce the ability of IRS-1 to transduce signals in the insulin signaling system." (PMID 35320949, 2022). "Insulin resistance results in hyperinsulinemia and hyperglycaemia which alongside chronic inflammation promotes endometrial tumorigenesis and metastasis by the direct pro-proliferative and anti-apoptotic effect of insulin and insulin growth factor (IGF-1) on endometrial cells." (PMID 35600348, 2022). "Therefore, it is suggested that there is a relationship between the incidence of obesity in PCOS and the increased risk of developing IR (Insulin Resistance) and T2DM, while high levels of circulating insulin stimulate the ovarian theca cells to produce androgens." (PMID 36364814, 2022). "Thus, multi-organ insulin resistance increases the demand for insulin from β cells." (PMID 35563490, 2022). "Therefore, in this study, blood plasma levels of glucose, insulin, and homeostatic model assessment for the insulin resistance (HOMA-IR) index were determined in all age groups of experimental animals fed a WD and compared to results in mice fed a standard diet (CTR)." (PMID 35563135, 2022).
Insulin resistance (continued). "The molecular mechanism of insulin resistance, and thus elevated insulin levels, is downstream of the insulin receptor (IR) in at least muscle, liver, and adipose tissue, and may be the result of the accumulation of ectopic lipids, including ceramides and/or diacylglycerols, in these tissues." (PMID 35244142, 2022). "Clinical studies of obese women with PCOS, employing weight loss programs, bariatric surgery, insulin-sensitizing agents in obese and non-obese patients, anti-androgens and mental health intervention, have diminished insulin resistance and improved ovulatory function." (PMID 35269778, 2022). "Similar observations are made for insulin since it is becoming increasingly apparent that neurons in the brain also become resistant to insulin; however, the relative contributions of central insulin resistance to the development of obesity and T2D remain poorly understood." (PMID 35958993, 2022). "In conclusion, the B. aegyptiaca fruit and seed aqueous extracts exhibit potential anti-hyperglycemic and anti-hyperlipidemic effects, which may be mediated by increasing the serum insulin levels, decreasing insulin resistance, and enhancing the anti-oxidant defense system in diabetic rats." (PMID 35213996, 2022). "Therefore, impairment of insulin secretion is more severe than insulin resistance." (PMID 35054888, 2022). "Collectively, our data show that β-cell insulin resistance in the form of reduced β-cell Insr contributes to hyperinsulinemia in the context of glucose stimulation, thereby improving glucose homeostasis in otherwise insulin sensitive sex, dietary and age contexts." (PMID 35136059, 2022). "Any abnormality in insulin signaling pathway may lead to insulin resistance." (PMID 35056765, 2022). "On the other hand, SUA may also induce insulin resistance via inhibiting the availability of nitric oxide and decreasing insulin-mediated glucose uptake in skeletal muscles, and the elevated SUA may damage islet B cells directly to aggravate insulin resistance." (PMID 35673358, 2022). "The observed inverse associations of birth weight with subsequent CVD risk in adulthood may reflect shared mechanistic pathways in utero where metabolic stress leads to insulin resistance, decreased leptin levels, and altered intracellular insulin signaling pathways." (PMID 35875812, 2022). "Suggested pathways that underpin the links between T2D and dementia may include systemic insulin resistance, and increased levels of circulating pro-inflammatory markers, which lead to defects in the insulin signaling pathway and changes in brain synaptic plasticity." (PMID 36514123, 2022). "Obesity, type 2 diabetes, and cardiovascular diseases share a common metabolic environment characterized by insulin resistance; therefore, regulating insulin resistance and secretion could be a key mechanism to prevent the aggravation of obesity and its related metabolic diseases." (PMID 35550138, 2022). "The mechanism of QTc prolongation in insulin resistance is still unclear but it is known that insulin may increase the transmembrane potential of cardiomyocytes by activating the electrogenic Na+/K+-ATPase leading to hyperpolarization and therefore QT prolongation." (PMID 35528832, 2022). "Therefore a disruption in the insulin signalling pathway could be another mechanism for diet-induced insulin resistance." (PMID 35676248, 2022). "The hypothesis of brain insulin resistance has historically been characterized by an overall reduction in insulin binding and downstream IR signaling, decreased brain insulin levels, and diminished insulin-mediated processes." (PMID 36009470, 2022). "However, increased circulating lipids due to decreased uptake in muscle could lead to insulin resistance, and insulin resistance in muscle could decrease anabolic signaling by insulin/IGF-1." (PMID 35159148, 2022).